FABP4 (fatty acid binding protein 4)
Diseases named in the same sentence as FABP4 in open-access papers (continued):
Sharing a sentence is not in itself a finding about the gene and the disease.
vitamin D deficiency (3 papers, 2018 to 2024). A nutritional condition produced by a deficiency of VITAMIN D in the diet, insufficient production of vitamin D in the skin, inadequate absorption of vitamin D from the diet, or abnormal conversion of vitamin D to its bioactive metabolites. "The experimental condition mimicking vitamin D deficiency upregulates adipogenic factors like peroxisome proliferator-activated receptor (PPAR)γ2 and fatty acid binding protein 4 (FABP4), both known to promote transition to adipogenesis." (PMID 33578813, 2021).
acute lung injury (2 papers, 2019 to 2022). A condition of lung damage that is characterized by bilateral pulmonary infiltrates (pulmonary edema) rich in neutrophils, and in the absence of clinical heart failure. "After suppressing FABP4 signaling, a protective effect was observed in mouse model with an acute lung injury (ALI)." (PMID 30969942, 2019).
adenoma (2 papers, 2018 to 2020). A neoplasm arising from the epithelium. "Restoration of Nudt7 by tail-vein injection into Nudt7−/− mice significantly reduced the development of adenoma observed in Nudt7−/− mice colons and the number of FABP4-, FASN-, Ki67-, CD45-, and SCD1-positive cells." (PMID 32131398, 2020). "We subsequently confirmed their modulation at the protein level by immunohistochemistry: cytoplasmic staining of CRABP1 was increased in follicular adenoma, and FABP4 expression was reduced in adenoma and further reduced in carcinoma." (PMID 29535811, 2018).
allergic asthma (2 papers, 2015 to 2022). A asthma with a basis in a pathological type I hypersensitivity reaction. "Previous studies have suggested that FABP4 protein plays a significant role in allergic asthma, although the exact mechanism underlying this effect is not clear." (PMID 26020772, 2015).
autism (2 papers, 2023 to 2025). Persistent deficits in social interaction and communication and interaction as well as a markedly restricted repertoire of activity and interest as well as repetitive patterns of behavior. "Some caution also arises from reports that FABP4 null mice were shown to exhibit autism-like behaviors relative to their controls, and that FABP4 levels are lower in children with autism." (PMID 37207357, 2023).
autoimmune disease (2 papers, 2021 to 2022). A disorder resulting from loss of function or tissue destruction of an organ or multiple organs, arising from humoral or cellular immune responses of the individual to their own tissue constituents. "Additionally, FABP4 has been implicated in the pathogenesis of several autoimmune disorders, including asthma and experimental autoimmune encephalomyelitis/multiple sclerosis." (PMID 33690220, 2021). "Our results demonstrated that treatment of NOD mice with the FABP4 inhibitors at an early age was sufficient to reduce the later development of autoimmune diabetes, suggesting that the therapeutic applications of the FABP4 inhibitors can be expanded into management of autoimmune diseases." (PMID 33690220, 2021).
cardiac arrest (2 papers, 2019 to 2020). Cessation of breathing and/or cardiac function. "To this end, we measured the plasma levels of four adipokines (adiponectin, leptin, fatty acid-binding protein 4 (FABP4), and visfatin) in 21 cardiac arrest patients at the admission and 2 or 7 days post ROSC." (PMID 32015774, 2020). "In the present study, we measured the plasma levels of four adipokines (adiponectin, leptin, fatty acid-binding protein 4 (FABP4), and visfatin) in cardiac arrest patients following return of spontaneous circulation (ROSC)." (PMID 32015774, 2020). "In this study, we selected four proinflammatory cytokines (adiponectin, resistin, FABP4, and visfatin), which have not been investigated in cardiac arrest yet, to explore their possible predict values in predicting outcome of patients post ROSC." (PMID 32015774, 2020).
cerebrovascular diseases (2 papers, 2019 to 2020). "The prognostic value of FABP4 in cardiovascular and cerebrovascular diseases was previously reported." (PMID 32075656, 2020).
cervical squamous cell carcinoma (2 papers, 2019 to 2020). A squamous cell carcinoma arising from the cervical epithelium. "Similarly, FABP4 promotes EMT in cervical squamous cell carcinoma (CSCC) cells, and FABP4 is specifically elevated in tissue samples from patients with CSCC but not with cervical adenocarcinoma." (PMID 33352874, 2020).
colitis (2 papers, 2015 to 2022). Inflammation of the colon. "To further illustrate the role of FABP4 in controlling pathogens, we infused GFP-labelled E. coli (1 × 109 CFUs) into mice, which are isolated from colitis tissues." (PMID 36519446, 2022).
colorectal tumor (2 papers, 2019 to 2022). "FABP4 is highly expressed in breast-invasive lobular carcinomas, and the expression level of FABP4 protein in colorectal tumor tissue is higher than that in cancer-adjacent tissue." (PMID 36532833, 2022). "Western blot analysis showed that the protein expression levels of FABP4 and FABP6 in colorectal tumor tissues were higher than those in adjacent tissues (FABP4: 1.103 ± 0.529 vs 0.746 ± 0.296, P < 0.001; FABP6: 0.988 ± 0.225 vs 0.521 ± 0.156, P = 0.002)." (PMID 31651326, 2019). "Immunohistochemistry showed that FABP4 and FABP6 were mainly distributed in the cytoplasm of human colorectal tumor tissues, and only a small amount distributed in adjacent tissues." (PMID 31651326, 2019). "The protein expressions of FABP4 and FABP6 were observed in colorectal tumor tissues and adjacent tissues by immunohistochemistry and western blot, respectively." (PMID 31651326, 2019).
diabetic cardiomyopathy (2 papers, 2020). Diabetic cardiomyopathy is a disorder of the heart muscle in people with diabetes. "We studied whether reduced FA uptake in the heart is protective against streptozotocin (STZ)-induced diabetic cardiomyopathy by using mice doubly deficient in fatty acid binding protein 4 (FABP4) and FABP5 (DKO mice)." (PMID 33257783, 2020).
diabetic retinopathy (2 papers, 2014 to 2019). "Lack of FABP4 expression in normal retinal vascular ECs makes FABP4 an attractive target for proliferative retinopathies, including retinopathy of prematurity and diabetic retinopathy." (PMID 24802082, 2014). "FABP4 shows clinically relevant potential as a novel predictor of diabetic retinopathy (DR)." (PMID 30857223, 2019).
esophageal cancer (2 papers, 2024 to 2025). A primary or metastatic malignant neoplasm involving the esophagus. "FABP4 is associated with epithelial-mesenchymal transition (EMT) and angiogenesis in esophageal cancer, contributing to tumor invasion." (PMID 40717587, 2025). "In esophageal cancer, FABP4 inhibits AMPK phosphorylation, activates mTOR signaling, and promotes tumor cell proliferation." (PMID 40717587, 2025).
fibrosis (2 papers, 2016 to 2023). the formation of excess fibrous connective tissue in an organ or tissue in a reparative or reactive process. "We also assessed the effect of FABP4 over-expression on pressure overload induced cardiac fibrosis, and the sizes of fibrosis area didn’t show significant difference." (PMID 27294862, 2016).
gastric tumor (2 papers, 2010 to 2022). "PD-L1 blockade decreases FABP4 and FABP5 expression in gastric tumor cells, while increases FABP4 and FABP5 expression in Trm cells, enhancing fatty acid uptake by Trm cells and sustaining survival of Trm cells." (PMID 35899119, 2022).
hepatitis B (2 papers, 2022). "Conversely, a study by Zhong and colleagues reports that patients diagnosed with HCC in the setting of underlying viral hepatitis B (HBV+) infection exhibit low FABP4 expression in HCC tissue, and that the level of FABP4 expression is associated with tumor size and overall survival." (PMID 36358315, 2022).
IgA nephropathy (2 papers, 2014 to 2018). "Furthermore, the level of FABP4 expression in the glomerulus was significantly higher in the patients with endothelial proliferative lesions than in those without the lesions in IgA nephropathy." (PMID 30513800, 2018). "Furthermore, the level of FABP4 expression in the glomerulus was significantly higher in patients with endothelial proliferative lesions than in those without the lesions in IgA nephropathy." (PMID 25506691, 2014).
iron deficiency (2 papers, 2016). "On d21.5 of gestation, the expression of placental lipase was unchanged by iron deficiency, however, the abundance of mRNAs for SREBP‐1c, FABP4 were reduced, suggesting that there were changes in fatty acid handling." (PMID 27905292, 2016). "It is probable, therefore, that decrease in the levels of THRSP, FASN, and FABP4 expression in the LowFe animals is an adaptation to a smaller quantity of iron, since iron deficiency, with or without anemia, harms thyroid metabolism." (PMID 27532424, 2016).
kidney injury (2 papers, 2018 to 2022). Trauma to the kidney. "So, these findings indicated that glycerol induced the upregulation of ER-related proteins in tubular epithelial cells, and BMS309403 suppressed FABP4 activity to reduce ER stress in glycerol-induced kidney injury." (PMID 30135658, 2018).
knee osteoarthritis (2 papers, 2021 to 2025). "While FABP4 has not been studied in the context of reovirus-induced arthritis or tenosynovitis, it has been described as a biomarker of human knee osteoarthritis, where patients exhibited significantly higher systemic and synovial FABP4." (PMID 41305511, 2025). "Fabp4 is a fatty acid-binding protein that serves as a biomarker for knee osteoarthritis." (PMID 33407721, 2021).
lymphedema (2 papers, 2023 to 2025). Excess fluid collection in tissues, causing swelling. "Patients with lymphedema also exhibited elevated levels of fatty acid-binding protein 4 (FABP4), a lipid chaperone associated with metabolic stress." (PMID 40759794, 2025). "Elevated levels of fatty acid-binding protein 4 (FABP4) were also detected in patients with lymphedema." (PMID 40759794, 2025). "Future studies will focus on further elucidating the molecular interactions between fatty acids, FABP4, and the lymphatic microenvironment to develop optimized treatments for lymphedema." (PMID 40759794, 2025). "Collectively, these findings suggest that SFAs and FABP4 contribute to lymphedema progression by promoting ER stress and oxidative stress, ultimately leading to apoptosis of LECs." (PMID 40759794, 2025). "Although a fivefold increase in FABP4 expression was observed in the HFD-fed lymphedema group compared to the CD group, this increase was less pronounced than the 6.8-fold increase in the HSFD-fed group." (PMID 40759794, 2025). "Lipotoxicity mediated by fatty acid-binding protein 4 (FABP4) contributes to secondary lymphedema pathogenesis." (PMID 40759794, 2025). "Immunofluorescence staining of tail sections showed increased FABP4 levels in the perilymphatic tissue of HSFD-fed mice with lymphedema compared to both their sham controls and mice in the CD and HFD lymphedema groups." (PMID 40759794, 2025). "Inhibiting FABP4 reduced stearic acid-induced damage in cells and mitigated lymphedema-related swelling and tissue injury in mice." (PMID 40759794, 2025). "Pharmacological inhibition of FABP4 with BMS markedly reduced lipid accumulation in HSFD-fed lymphedema mice, reaching levels comparable to those observed in sham-operated or CD-switched animals (Fig. EV4A,B)." (PMID 40759794, 2025). "Lymphedema samples exhibited aberrant expression of metalloproteinases such as ADAMTSL1 and a decrease in transcripts associated with adipocyte identity (FABP4, CD36)." (PMID 38131378, 2023). "FABP4 levels were 2.8-fold higher in individuals with lymphedema compared to controls." (PMID 40759794, 2025). "Our findings suggest that targeting FABP4, through dietary intervention or pharmacological inhibition, may represent a novel therapeutic strategy for lymphedema management." (PMID 40759794, 2025). "Additionally, HSFD feeding significantly increased circulating FABP4 levels in mice with lymphedema compared to those fed a CD, whereas FABP4 inhibition with BMS attenuated this elevation in HSFD-fed animals (Fig. EV4F)." (PMID 40759794, 2025). "Nevertheless, given its dual role in promoting cancer proliferation and contributing to lymphedema, FABP4 inhibition represents a compelling therapeutic strategy with the potential to address both cancer-related lymphedema and the metabolic alterations associated with cancer progression." (PMID 40759794, 2025). "This research suggests that dietary interventions to reduce SFAs and therapeutic targeting of FABP4 may offer new strategies to manage or prevent lymphedema, improving outcomes and quality of life for affected patients." (PMID 40759794, 2025). "We first measured circulating FABP4 levels in plasma samples from patients with lymphedema and non-lymphedema controls." (PMID 40759794, 2025).
lymphoma (2 papers, 2021 to 2025). A malignant (clonal) proliferation of B- lymphocytes or T- lymphocytes which involves the lymph nodes, bone marrow and/or extranodal sites. "The increased TAG level in DCs of lymphoma mouse or patients with lymphoma is mainly realized by regulating the expression levels of scavenger receptor A, lipoprotein lipase, and fatty acid-binding protein 4, and promoting the uptake of TAG in BMDCs and moDCs." (PMID 33732237, 2021).
macular holes (2 papers, 2021). A hole in the macula of the retina. "In the current study, to elucidate the pathological involvement of FABP4 within the PDR, we surgically collected vitreous specimens from patients with PDR or non-PDR (epiretinal membranes or macular holes) and measured the FABP4 and VEGF concentrations in these samples." (PMID 34117325, 2021). "In the current study, to elucidate the pathological involvement of FABP4 within the RVO, we surgically collected vitreous specimens from patients with RVO or non-RVO (epiretinal membranes or macular holes) and measured the FABP4 and VEGF concentrations in these samples." (PMID 33503066, 2021).
metastatic prostate carcinoma (2 papers, 2013 to 2016). A carcinoma that arises from the prostate gland and has spread to other anatomic sites. "FABP4 is a prognostic predictor in infiltrating or invasive bladder cancer, and FABP4 is a potential therapeutic target for metastatic prostate cancers." (PMID 27323829, 2016). "Together, our data provide evidence for functional relationship between bone marrow adiposity and metastatic prostate cancers and unravel the FABP4/IL-1β axis as a potential therapeutic target for this presently incurable disease." (PMID 24240026, 2013).
oligodendroglioma (2 papers, 2023 to 2024). A well-differentiated (WHO grade II), diffusely infiltrating neuroglial tumor, typically located in the cerebral hemispheres. "Oligodendrogliomas grade 2 and 3 and astrocytomas grade 2 and 3, in general, exhibited low FABP4 and low GFAP values." (PMID 38879494, 2024).
oral squamous cell carcinoma (2 papers, 2022). "In an in vitro study, FABP4 expression was found to play an important role in oral squamous cell carcinoma cell growth through the MAPK pathway." (PMID 36532833, 2022).
paroxysmal AF (2 papers, 2020 to 2022). "Our previous findings showed an association of both local and peripheral FABP4 (a carrier protein for fatty acids) concentration levels with left atrial adipose tissue volume in persistent but not in paroxysmal AF patients." (PMID 32767737, 2020).
renal carcinoma (2 papers, 2022 to 2023). A carcinoma arising from the epithelium of the renal parenchyma or the renal pelvis. "In addition, PPARG signaling activation causes lipolysis mediated by FABP4 and inhibits lung and renal cancer cell growth." (PMID 36114448, 2022). "It was suggested that the release of FABP4 in kidney cancer tissues might be different from that in normal kidney tissues, which might be one of the potential characteristics of renal cancer cells." (PMID 37260987, 2023).
renal fibrosis (2 papers, 2020 to 2024). A final common manifestation of a wide variety of chronic kidney diseases characterized by glomerulosclerosis and tubulointerstitial fibrosis. "In this process, serum amyloid A1 (Saa1) is a gene directly regulated by FABP4 in the MMT process of renal fibrosis." (PMID 39445007, 2024). "In this study, we confirmed that genetic and pharmacological inhibition of FABP4 alleviated renal fibrosis in UUO mice." (PMID 33101287, 2020). "Therefore, we next hypothesized that Saa1 may serve as a FABP4 target gene during the process of MMT-mediated renal fibrosis." (PMID 33101287, 2020). "The main pharmacological interventions for attenuating renal fibrosis through MMT are tFNAs, HJHR, vitamin D, PTB, ERS inhibitors, MRS1754, MBL, and FABP4." (PMID 39445007, 2024). "The result also confirmed that FABP4 correlated with interstitial fibrosis in IgAN patients and highlighted an active role for FABP4 regulating MMT cells in the process of renal fibrosis." (PMID 33101287, 2020). "In view of the need for developing therapeutic agents for the treatment of renal fibrosis, we assessed the effect of a highly selective inhibitor BMS309403 against FABP4 on the expression of ECM deposition and fibrotic markers in the kidneys of UUO mice." (PMID 33101287, 2020).
sarcoidosis (2 papers, 2020 to 2021). Sarcoidosis is a multisystemic disorder of unknown cause characterized by the formation of immune granulomas in involved organs. "FABP4, was previously proposed as sarcoidosis candidate gene." (PMID 33276795, 2020). "Among those dysregulated transcripts, we validated 46 in TB and 44 in sarcoidosis, 14 of them differentially expressed in lung, 30 in lymph nodes and 4 genes dysregulated in both tissues ADAMST1, CXCL2, CXCL9, FABP4." (PMID 33276795, 2020). "This study corroborates previous genomic markers suggested for sarcoidosis such as STAB1, HBEGF, FABP4 and NOTCH4, with HBEGF and NOTCH4 only expressed in lung granulomas." (PMID 33276795, 2020). "Interrogation of the expression levels of these 10 sarcoidosis genes to TB and CM DEGs revealed CCL14, CXCL9, FABP4, NR1H3 were also significantly dysregulated in TB." (PMID 33276795, 2020).
scleroderma (2 papers, 2021 to 2023). Scleroderma is a rare autoimmune connective tissue disorder characterized by abnormal hardening of the skin and, sometimes, other organs. "In addition, downregulated adipogenic markers peroxisome proliferator activated receptor-γ2 (PPARγ2), fatty acid-binding protein 4 (FABP4) and adiponectin) as well as reduced thickness and total volume of dermal white adipose tissue (dWAT) were detected in skin from scleroderma mouse models." (PMID 33897433, 2021). "Genes associated with ECM components, such as COL4A1, heparan sulfate proteoglycan 2 (HSPG2), and actin beta (ACTB), as well as phospholipase C gamma 2 (PLCG2), fatty binding protein 4 (FABP4), and galectin 1 (LGALS1), also showed higher expression levels in scleroderma." (PMID 37443817, 2023). "PLCG2, FABP4, and LGALS1, which are involved in inflammatory pathways as well as pathways regarding leukocyte transendothelial migration, vascular smooth muscle contraction, and the pro-inflammatory PPAR signalling pathways that were upregulated were also upregulated in scleroderma ECs." (PMID 37443817, 2023).